GDF15 (growth differentiation factor 15)
Diseases named in the same sentence as GDF15 in open-access papers (continued):
Sharing a sentence is not in itself a finding about the gene and the disease.
cancer (continued). "The fact that GDF-15 plays a role in the induction of cancer epithelial-to-mesenchymal transition (EMT) also suggests the possibility that agarwood-NE may possess anti-cancer or anti-metastatic activity." (PMID 36839377, 2023). "The baseline measurements likely reflect the increases in GDF15 caused by tissue damage to the body caused by cancer itself as GDF15 is released, non-specifically, as a result of tissue injury." (PMID 38146512, 2023). "GDF15 also drives cancer cachexia, a disease with similar symptoms to HG." (PMID 36536797, 2023). "Moreover, GDF15 is considered the main actor of cachexia in cancer signaling through its receptor GFRAL." (PMID 37691636, 2023). "Neutralizing GDF15 has shown good promise in alleviating cachexia symptoms and could represent a target for targeting symptoms in children with cancer." (PMID 38146512, 2023). "Comparison of GDF15 in participants with cancer at both baseline and 3-month follow-upa." (PMID 38146512, 2023). "Our study found higher levels of GDF15 in children with cancer compared to the controls (p<0.001)." (PMID 38146512, 2023). "GDF15 overexpression can be both chemotherapy- and cancer-driven." (PMID 37495707, 2023). "Interestingly, a GFRAL‐blocking monoclonal antibody has been shown to reverse cancer cachexia in mouse models, thus corroborating the fundamental role of GDF15 in weight maintenance." (PMID 36992609, 2023). "Recently, GDF15 was shown to be induced in many cell types under conditions of stress, such as metabolic disease (diabetes and obesity), inflammation, infection, cardiovascular disease, and cancer." (PMID 36472770, 2023). "However, GDF-15 is also known to be pleotropic with opposing effects that can lead to proliferation of cancer cells." (PMID 36844723, 2023). "However, the regulatory role of GDF15-GFRAL-RET signalling axis in cancer chemoresistance is unexplored." (PMID 37814317, 2023). "We further found that the expression of GDF15 but not IL1A was positively associated with the logIC50 of sunitinib using Genomics of Drug Sensitivity in Cancer (GDSC) and Cancer Genome Project (CGP) datasets." (PMID 36720918, 2023). "Hence, it would be important to reduce GDF15 expression not only in cancer cells but also in cardiomyocytes that overexpress GDF15 because of drug toxicity." (PMID 37495707, 2023). "GDF-15 is involved in the stress response and is known to be overexpressed by most cancers." (PMID 37781173, 2023). "Interestingly, we noticed that Ferroptosis (WP4313), which has recently attracted much attention in the cancer research community, was significantly enriched among the pathways that were positively correlated with GDF15 expression." (PMID 38082448, 2023). "Resulting GDF-15 expression levels were similar to those observed in human cancer cell lines." (PMID 37474523, 2023). "In addition, there are several signaling pathways including AKT, ERK, p38, and NF-κB that are regulated by GDF15 in other cancers." (PMID 36769245, 2023). "Moreover, most of the investigations conducted on GDF15 SNPs have focused on cardiac and cancer pathologies, although GDF15 appears to be a metabolic master regulator." (PMID 36992609, 2023). "This study was therefore designed to understand the molecular basis of drug-specific and cell type-specific regulation of GDF15 gene induction and suppression by screening cardiotoxic drugs in human cardiomyocytes and analyzing in-house and public gene signatures database of cancer cell lines." (PMID 37495707, 2023). "The role of mitokines such as GDF15 in cancer development and progression thus may be cancer‐specific and differentially amenable to exercise interventions and needs continued exploration and refinement." (PMID 36642986, 2023). "Additionally, in adult survivors of pediatric cancers, GDF15 appears to predict early anthracycline-induced cardiac toxicity, but no studies of GDF15 at childhood cancer diagnosis or during cancer therapy have been performed." (PMID 38146512, 2023).
cancer (continued). "Furthermore, there are very little existing data on GDF15 levels in children with cancer, let alone based on individual cancer diagnoses." (PMID 38146512, 2023). "Additionally, elevated levels of circulating GDF15 have been discovered in several malignant tumors and are considered potential tumor biomarkers." (PMID 36769245, 2023). "GDF15 may also play a part in cancer development and progression depending upon cancer type, stage, and microenvironment." (PMID 35853851, 2022). "In the last two decades, GDF15 has attracted significant attention in biological and medical fields owing to its multiple roles in a variety of diseases, including cardiovascular disease and cancer." (PMID 35721026, 2022). "GDF-15 represents a promising target both for the reversal of cancer cachexia and for the enhancement of an antitumor response, however, additional research is needed to further elucidate its potential either as a single therapy or in combination with existing immunotherapies." (PMID 35743911, 2022). "Similar to other TGFβ superfamily members, this discrepancy may be due to the tumor suppressor activity of GDF15 in the early stages of tumor formation and its stimulative effect on cancer cell migration and invasion during tumor progression." (PMID 35694408, 2022). "Overall, these data suggested that muscle atrophy in cancer cachexia was related to activation of apoptosis while GDF-15 might induce apoptosis in muscle tissues via activating Bcl-2/caspase-3 pathway." (PMID 35379793, 2022). "Pro-tumorogenic effects of GDF15 have been linked with increased activity of different signaling pathways (PI3K/AKT, MAPK/ERK, TGF-β/SMAD), but apart from mediating cancer-induced cachexia, a role for GDF15/GFRAL axis in cancer remains to be determined." (PMID 35694408, 2022). "It is worth mentioning that the PI3K-AKT pathway including EGFR is reported to be activated in many human cancer types and whether GDF15 acts as a suppressor or promoter related to EGFR expression in PCa remains unresolved." (PMID 35853851, 2022). "However, the role of GDF-15 in cancers is ambiguous by exerting pro-tumorigenic and anti-tumorigenic functions." (PMID 35963873, 2022). "GDF-15 is a critical regulator involved in cancer progression and migration." (PMID 35963873, 2022). "In conclusion, our study indicates the possibility that locally administered lidocaine for pain control in cancer patients might suppress tumor growth by increasing GDF-15 and TRIB3 expression." (PMID 36008442, 2022). "Thus, the levels of GDF15 are greatly elevated in various types of cancers including breast, ovarian, cervical, prostate, colorectal, gastric, and pancreatic." (PMID 35694408, 2022). "Additionally, GDF-15 was reported to be overexpressed in cancer cells of various origins, including predominantly prostatic, renal, urothelial, colorectal cancers and melanoma." (PMID 35251002, 2022). "Therefore, GDF15 is regarded as a prognostic biomarker in cancer, inflammatory diseases, and cardiovascular complications." (PMID 36444166, 2022). "As a stress response protein, GDF-15 can be induced universally under the conditions of injury, inflammation and malignancy leading to modest increases in many disease processes and especially advanced cancers." (PMID 35379793, 2022). "Increased blood levels of GDF-15 are related to stressogenic events, anoxia and acute injury, and are found to be increased in several diseases including inflammation, obesity, cardiovascular disease and cancer." (PMID 35872912, 2022). "In support to the hypothesis that T2D, senescence and cancer are related, T2D patients present circulating GDF15 levels that are three times higher compared to the healthy controls (p < 0.001)." (PMID 36059680, 2022).
cancer (continued). "Furthermore, GDF15 is also released by the cancer therapeutic drug cisplatin to mediate anorectic signaling." (PMID 34784295, 2022). "A study of the effect of GDF-15 through glial cell-derived neurotrophic factor (GDNF) family receptor α-like protein (GFRAL) demonstrated that increased GDF-15 is related to the anorexia/cachexia observed in advanced cancer patients." (PMID 36008442, 2022). "Moreover, treatment with diltiazem in tumor-bearing mice also decreases cancer metastasis and nodule formation, with more GDF-15 expression in diltiazem-treated mice than saline-treated mice, respectively." (PMID 35963873, 2022). "Consequently, GDF15 is observed as a prognostic biomarker in cancer, inflammatory diseases, and cardiovascular complications." (PMID 36140453, 2022). "It is hypothesised that upregulation of GDF-15 combined with decreased expression of FOXM1 act together to form a CBD-dependent antiproliferative pathway across numerous cancer types." (PMID 35954477, 2022). "The GDF15–GFRAL axis is a promising target for the study of cancer cachexia." (PMID 36105371, 2022). "GDF15 has served as a biomarker for cancer tumorigenesis, prognosis, and progression." (PMID 36353620, 2022). "In addition to direct effects on cancer cells, GDF15 exerts effects on anti-tumor immunity and/or angiogenesis by modulating the tumor microenvironment." (PMID 35694408, 2022). "Results of the present study suggested that GDF-15 contained in tumor-derived exosomes might be involved in muscle wasting in cancer cachexia via inducing apoptosis of myocytes." (PMID 35379793, 2022). "GDF15, a distant member of the transforming growth factor-β family, is upregulated in response to cellular stress and several diseases, including cancer." (PMID 35916366, 2022). "The proposition of GDF-15 as a useful biomarker for cancer is long-standing." (PMID 36361969, 2022). "GDF15 has been established as a nexus for key hallmarks of cancer across numerous cancer types, and future work may entail exploring GDF15 signaling as a potential therapeutic target." (PMID 36353620, 2022). "GDF15 was initially thought to be a macrophage inhibitory cytokine but it was later proven that its increase indirectly contributes to iron overload in cancer patients and those with sideropenic anemia by downregulating hepcidin expression and increasing iron absorption." (PMID 35052868, 2022). "GDF-15 also suppresses macrophage anti-tumor responses during early cancer development." (PMID 35821815, 2022). "Antibodies against the receptor for GDF15 reverses cancer cachexia in mice." (PMID 34784295, 2022). "Moreover, exosomes secreted by C26 colon cancer cells were enriched with GDF-15 and found to contribute to the development of cancer cachexia by inducing muscle atrophy via regulating Bcl-2/caspase-3 pathways." (PMID 35994202, 2022). "Indeed, GDF15 is overexpressed in various cancer cell types including renal, prostatic, colorectal, urothelial and melanoma." (PMID 36140453, 2022). "However, the role of GDF-15 in cancer development and progression depends on the cancer type, stage, and tumor microenvironment." (PMID 36230513, 2022). "Cancer cell stemness, proliferation, migration, and invasion can be directly affected by GDF15." (PMID 35694408, 2022). "However, the role of GDF-15 is disputed among cancers since it involves in tumor behaviors both positively and negatively depending on the cellular state and environment." (PMID 35963873, 2022). "To further support our observation, we investigated GDF15 expression in cancer patients." (PMID 35853851, 2022). "GDF-15 is highly overexpressed in colorectal, ovarian, lung, and many other cancer types, and is therefore considered a promising biomarker for cancer prognosis in addition to its potential role in cancer cell evasion of anti-tumor immune responses." (PMID 35821815, 2022).
cancer (continued). "Additionally, GDF15 is elevated in various types of cancers, most prominently in prostate, urothelial, renal, melanoma, and colorectal cancers." (PMID 35806366, 2022). "The GDF15 was concerned with the development of different cardiometabolic disorders and cancer." (PMID 36140453, 2022). "The RT-qPCR analysis revealed that GDF15 was expressed in normal bladder epithelial cells and stromal cells with higher levels of GDF15 in HBdSMC and HBdEC, with RT-4 cells having the highest and TSGH-8301 cells having the lowest level of GDF15 among the carcinoma cells." (PMID 34662721, 2022). "Circulating GDF15 concentrations in advanced cancers are in the range of 10–100 ng/mL." (PMID 34831213, 2021). "In the BMI range of <22.5 kg/m2, patients with elevated GDF-15 were associated with increasing hazard for all-cause death and more than a 4-fold increased risk of cancer and CV death as compared with those with non-elevated GDF-15." (PMID 34150865, 2021). "Elevated levels of GDF15 have been linked to tumor growth and poor prognosis in cancer patients raising the question as to whether GDF15 serves as a tumor suppressor or promoter and a target for the treatment of cancer." (PMID 34421827, 2021). "Recent evidence suggests that macrophages acquiring M2‐like characteristics may upregulate GDF‐15 expression in human cancer." (PMID 33784024, 2021). "Finally, we combined Genomics of Drug Sensitivity in Cancer (GDSC) and Cancer Therapeutics Response Portal (CTRP) analyses to identify that Gemcitabine acts to simulate the GDF15 gene profile and is a potential candidate for the treatment of COAD." (PMID 34948431, 2021). "Interestingly, PLA2G7 protein and activity levels were more efficient to discriminate between cachectic and non‐cachectic cancer patients than IL‐6 and GDF‐15, two other factors proposed as biomarkers for CCx diagnosis." (PMID 34427055, 2021). "Due to the complex contribution of cancer and host factors, combination therapy including GDF15 blockade along with chemotherapy/immunotherapy will likely be needed to reverse cachexia metabolic signature, which in turn will improve the lives of persons living with cancer." (PMID 33442410, 2021). "Consistently, it was shown that the MLK3/GDF15 axis serves an important role in inducing cancer cachexia; thus, inhibition of MLKs may suppress the tumor-derived factors involved in cachexia." (PMID 34439974, 2021). "• GDF15 a putative prognostic indicator of tumor progression and therapeutic target and raising the question as to whether GDF15 serves as a tumor suppressor, or as a promoter and is a target for the treatment of cancer." (PMID 34421827, 2021). "The TIMER2.0 analysis demonstrated that GDF15 had significant negative correlations with total macrophage, macrophage M1, macrophage M2, cancer-associated fibroblast, and endothelial cells." (PMID 34948431, 2021). "Therefore, results from ongoing clinical trials in human models inhibiting the GDF15/GFRAL pathway will shed light on patients with cancer cachexia." (PMID 33442410, 2021). "To investigate whether miR-216a and GDF15 have a broad value, we performed a series of studies on miR-216a and GDF15 across all cancer types." (PMID 34948431, 2021). "In addition, IGFBP7 and more so GDF-15 predicted cancer mortality (147 events, 27.9% of all deaths)." (PMID 34217226, 2021). "Several studies report higher expression of GDF15 mRNA and protein in cancer biopsies." (PMID 34445593, 2021). "The expression of GDF15 in cancer cell lines results in cell growth arrest and increased apoptosis, which suggests that GDF-15 may have antitumorigenic activity." (PMID 34920697, 2021). "Globally, considering both host and cancer factors, only the completion of clinical trials using an inhibitor of the GDF15/GFRAL pathway will provide clinical evidence on the merit of reversing this “metabolic signature” to improve the lives of those living with advanced cancer." (PMID 33442410, 2021).
cancer (continued). "In the sensitive analyses, we got the similar results, however, the association of GDF-15 with the risk of all-cause and cancer death became no longer statistically significant in the groups of high BMI." (PMID 34150865, 2021). "In a normally functioning human body, the expression of GDF15 exhibits tissue specificity, primarily distributed in the prostate, kidney, and pancreas, although its expression is increased at the kidney and liver lesions of several cancers." (PMID 34948431, 2021). "Previous studies on GDF-15 suggested its divergent roles in cancer metastasis." (PMID 34070192, 2021). "The caveat to this is that the secretion of GDF15 during cancer, as it appears so for inflammatory infections, is presumably an adaptive response, so blocking GDF15/GFRAL signalling may worsen the disease and other symptoms." (PMID 32723474, 2020). "Moreover, cancer cachexia involves several mediators produced from the cancer cells and the tumor microenvironment, i.e., pro-inflammatory mediators including GDF-15." (PMID 33396237, 2020). "While it is already clear that cancer types with the reportedly highest levels of GDF-15 are less prone to benefit from such single-agent immunotherapies, a possible role for GDF-15 in the evolving landscape of biomarkers for checkpoint inhibitor immunotherapy remains to be established." (PMID 32508832, 2020). "Six were common for cancer stage (Up: GDF15, TIMP1, IL1RL1; Down: CCL22, APP, CLEC1B)." (PMID 33334063, 2020). "The described associations and mechanistic data support the hypothesis that GDF-15 acts as immune checkpoint and is thus an emerging target for cancer immunotherapy." (PMID 32508832, 2020). "The median GDF-15 circulating levels were not different between cancer patients with body weight loss vs. patients with stable body weight (6.86 vs. 6.68) (p = 0.258)." (PMID 33396237, 2020). "One potential mechanism that may explain the differences in the action of GDF15 on early and advanced cancer and the differences in the data from induced or transgenic cancer models and mouse tumor xenograft models is modulation of antitumor immunity." (PMID 32502202, 2020). "It is known that IL6 and GDF15 serve as key mediators of cancer cachexia." (PMID 33182625, 2020). "Thus, the definitive role of GDF-15 in cancer and its possible role in immunotherapy remain to be elucidated." (PMID 32508832, 2020). "GDF-15 thus impairs two essential steps in the so-called Cancer Immunity Cycle." (PMID 32508832, 2020). "The various reports on GDF-15 promoting stemness in cancer cells might thus be explained by GDF-15 shaping the tumor microenvironment." (PMID 32508832, 2020). "A contemporary study has confirmed the role of GDF15 in mouse models of cancer cachexia." (PMID 32310257, 2020). "Elevated GDF-15 levels in cancer patients have been frequently reported." (PMID 32508832, 2020). "The role of GDF15 in cancer cachexia has been known for over a decade." (PMID 32310257, 2020). "Premature or biological immunosenescence with accompanying “inflammaging” might represent other possible mechanisms, relating GDF-15 to multiple age-related phenotypes and pathologies like OA, cancer, neurodegenerative disorders, frailty, or CVD." (PMID 32993054, 2020). "This suggests that further studies may be warranted to determine if GDF15 has application as a stimulator of tumor immunity, in the therapy of cancer." (PMID 32502202, 2020). "Additionally, utilizing the mutant adenomatous polyposis coli (APC) gene mouse model of colonic polyps and cancer, mice overexpressing GDF15 are protected from the development of polyps and cancer." (PMID 32502202, 2020). "GDF-15 is among the most widely overexpressed proteins in human cancer." (PMID 32508832, 2020). "One might speculate that GDF-15 could play a dual (deleterious and protective) role in a variety of settings, as it e.g., has been recently proposed for cancer." (PMID 32993054, 2020).